IL18 (interleukin 18)
Diseases named in the same sentence as IL18 in open-access papers (continued):
Sharing a sentence is not in itself a finding about the gene and the disease.
depression (137 papers, 2006 to 2026). "A 2023 large-scale two-sample MR study analyzing 41 inflammation-related factors across over 130,000 depression cases found that only a few cytokines, such as IL-18, IL-1β, and RANTES, exhibited protective associations with depression risk." (PMID 41561993, 2025). "The primary cytokines linked to depression consist of various indicators like Tumor Necrosis Factor α (TNFα), Interleukin (IL)-1β, IL-18, and Interferon (INF)-γ." (PMID 38731995, 2024). "A longitudinal study following post stroke patients reported that plasma levels of IL-18 were independently associated with the development of minor and major depression." (PMID 37252156, 2023). "Several studies have reported that caspase 1, IL-1β, and IL-18 are associated with depression, anxiety, and fatigue, indicating the implication of the NLRP3 inflammasome in the pathophysiology of these diseases." (PMID 36675440, 2023). "IL-18 has been extensively studied in post-stroke mice with the evidence supporting that IL-18 predicts the risk of developing depression." (PMID 37252156, 2023). "IL-18 is expressed in the brain, and it is increased in patients with depression and influences stress-related susceptibility to mood and anxiety symptoms by changing amygdala reactivity." (PMID 37510364, 2023). "The PCLO rs2715157 has been primarily established in MDD GWAS in Europeans, while IL18 rs187238 was associated with clinical depression, and a differential expression level of IL18 gene was related to rs187238 genotypes." (PMID 37510260, 2023). "Lastly, our study was unable to evaluate some immune markers and cytokines previously linked to WNV infection such as IL-2, IL-4, IFN-B, TLR-3, IL-11, and IL-18, as well as some previously linked to depression such as IL-18 and NFκB." (PMID 35745504, 2022). "Depression exhibited increases in IL-1β and IL-18 levels associated with activation of NLRP3 inflammasome." (PMID 35069768, 2022). "In our previous studies, we found that IL18 was associated with energy metabolism and psychiatric disorders such as depression." (PMID 36151082, 2022). "Interleukin-18 (IL-18) is an inflammatory cytokine that has been linked to energy homeostasis and psychiatric symptoms such as depression and cognitive impairment." (PMID 34708129, 2021). "We previously revealed that deficiency in IL-18 led to hippocampal abnormalities and resulted in depression-like symptoms." (PMID 34708129, 2021). "To examine which genes were responsible for causing depression under IL-18-deficit conditions, we searched for molecules expressed in both CMS and Il18−/− mice." (PMID 34708129, 2021). "Higher concentrations of IL-6 and IL-18 were also independently associated with depressive disorders in patients after stroke, and depression severity correlated positively with serum concentrations of IL-6 and IL-18 in hemodialyzed patients." (PMID 30092066, 2018). "Further, physical and emotional stress can also elevate IL-18 levels, making IL-18 a susceptibility factor for depression, another condition associated with an increased risk of an array of neurodegenerative diseases and processes." (PMID 28531131, 2017). "IL-18 is also induced during physical/emotional stress responses, and is a susceptibility factor for depression, another condition that is intimately associated with neurodegenerative processes." (PMID 25147500, 2014). "This would also be consistent with the findings of one previous study, in which elevated IL-18 concentrations were associated with poststroke depression." (PMID 25054133, 2014). "It is interesting that those peripheral cytokines that predict emergence of depression after a stroke (e.g., IL-18) differ from the key cytokines typically implicated in depressive illnesses that occur in other circumstances (e.g., IL-6, TNF-α, or IL-1β)." (PMID 23675319, 2013).
depression (continued). "With respect to inflammation, only the somatic symptom dimension of depression was consistently associated with elevated levels of IL-18, IL-1-Ra, fibrinogen, CRP and decreased albumin levels." (PMID 23967272, 2013). "The serum levels of IL-18 were also significantly higher in moderate-severe depression patients, further suggesting that the pathophysiology of depression is associated with an inflammatory response involving IL-18." (PMID 20113500, 2010). "High IL-18 levels may heighten susceptibility to poststress depression and interact with serotonin (5-HT) to affect brain function and trigger emotional disorders." (PMID 41194915, 2025). "The interaction between IL-18 and the kynurenine pathway, which is involved in tryptophan metabolism, may also contribute to serotonin deficiency, a feature of depression." (PMID 40305200, 2025). "It has been reported that AHSG protein levels are elevated in the prefrontal cortex and hippocampus of rats under chronic mild stress (CMS), as well as in the serum of IL-18-deficient mice with a depression-like phenotype, suggesting a potential role of AHSG in MDD." (PMID 38049858, 2023). "This may suggest that serum IL-18 determination on day 7 after admission may predict the risk of post-stroke depression both in the acute stage of stroke and 6 months after stroke." (PMID 37509542, 2023). "Similarly, our study also revealed a significant inverse association between genetically proxied IL-18 concentrations and major depressive disorder (MDD)." (PMID 37600668, 2023). "We previously found that IL18 deficiency may cause hippocampal impairment, resulting in depression-like behavioral changes." (PMID 36151082, 2022). "This study aimed to explore whether IL-18 correlates with areas of the brain associated with depression." (PMID 35931995, 2022). "In addition, increases in the NLRP3 inflammasome and caspase-1 levels are associated with increases in serum IL-1B and IL-18 levels in patients with major depression." (PMID 34422020, 2021). "Hence, we herein sought to determine the molecular expression based on the development of depression in the condition of IL-18 deficiency, especially focusing on the PFC." (PMID 34708129, 2021). "IL-18 is associated with energy metabolism and psychiatric disorders such as depression." (PMID 34708129, 2021). "Thus, IL-18 is closely associated with the immune system, energy balance, neural function, and depressive disorders." (PMID 34708129, 2021). "Moreover, plasma IL-18 concentrations have also been linked to the availability of μ-opioid receptor in patients with major depression." (PMID 30092066, 2018). "High concentrations of interleukin 18 and low concentrations of 25-hydroxyvitamin D3 may be associated with depression severity in men with psoriasis." (PMID 30092066, 2018). "In patients with depression, pathogen-associated molecular patterns (PAMPs) such as inducible nitric oxide synthase (iNOS) and nitric oxide (NO), and danger-associated molecular patterns (DAMPs) such as IL-1β and interleukin-18 (IL-18) enter the cytoplasm of hippocampal microglia." (PMID 39114351, 2024). "In addition, IL-18 has been linked to inflammation and depression." (PMID 37252156, 2023). "The NLRP3 inflammasome, a key inflammatory signaling platform of the innate immune system, mediates the maturation and release of IL-1β and IL-18 and induces pyroptosis, playing a significant role in both depression and CVD." (PMID 41194915, 2025). "In the AB group alone, IL‐8 negatively correlated with anxiety/depression measures, and IL‐18 positively correlated with AUD severity measures." (PMID 40317574, 2025). "Research indicates that upon the activation of NLRP3, factors such as GSDMD, IL-1β, and IL-18 collectively contribute to the pathogenesis of depression." (PMID 41194915, 2025).
depression (continued). "Evidence indicates that the NLRP3 inflammasome significantly contributes to the pathogenesis of depression by activating proinflammatory cytokines such as IL-1β and IL-18, which also play pivotal roles in the development of CVD." (PMID 41194915, 2025). "The inhibitor MCC950 reduced NLRP3, IL-1β, and IL-18 levels in the hippocampus and improved depression behavior." (PMID 41048915, 2025). "Exploratory analyses in combined groups showed that measures of past drinking, AUD severity, and anxiety/depression positively correlated with IL‐18 and TNF‐α and negatively correlated with BDNF." (PMID 40317574, 2025). "This, in turn, suppresses the activation of caspase-1 and decreases the production of IL-1β and IL-18, thereby improving mitochondrial energy metabolism and alleviating depression." (PMID 40699781, 2025). "Several animal studies reported that depression-like behaviour in OVX animals was associated with NLRP3 inflammasome activation and enhanced IL-1β, IL-18, TLR4 and NF-κB expression in the hippocampus (Refs 153,163,164,165)." (PMID 40905280, 2025). "For example, patients with psoriasis and comorbid depression have shown elevated serum concentrations of IL-6, IL-18, and IL-17A." (PMID 40077004, 2025). "Meta-analyses indicated an increase of inflammatory biomarkers such as IL-6, IL-18 in depression but regarding TNF-α there were inconsistent reports." (PMID 39717874, 2025). "Our CytoHubba analysis identified six hub genes (PECAM1, TLR2, PTGS2, LRRK2, HCK, and IL18), all significantly upregulated in both depression and hypovitaminosis D, with PTGS2 having the highest inference score and reference count." (PMID 38256187, 2024). "Specifically, greater levels of proinflammatory cytokines (i.e., tumor necrosis factor- (TNF-) and interleukin-18 (IL-18)) have been shown to relate to the severity of agitated depression." (PMID 39199439, 2024). "Activation of NLRP3 and increased secretion of IL-1β and IL-18 are essential pathophysiological mechanisms of depression." (PMID 38627683, 2024). "To confirm the presence of inflammation in rats with MI and depression, we quantified the levels of IL‐1β, IL‐18, and TNF‐α in rat serum using ELISA." (PMID 38970230, 2024). "IL-18 can increase due to activation of the HPA axis and has been linked to brain disorders such as depression and cognitive impairment." (PMID 38796504, 2024). "In ovariectomised mice, forced treadmill exercise for one week was found to reduce depression-like behaviours (as observed in a sucrose preference test and a forced swim test) by reducing IL-1β and IL-18 levels in the hippocampus." (PMID 38560580, 2024). "Consistent with this, Si-ni San inhibited the expression of IL18, which also contribute to the improvement of depression combined with anxiety." (PMID 39247617, 2024). "The RvD1, NLRP3, IL-1β, IL-18, and IL-4 serum levels were dynamically evaluated before and after 6-8-week anti-depression treatment." (PMID 38627683, 2024). "The preclinical data strongly support a central role for IL-18 in the development of depression post brain injury." (PMID 37252156, 2023). "High levels of IL-1β and IL-18 deplete synaptic serotonin, dopamine and norepinephrine, contributing to depression, particularly anhedonia." (PMID 37206541, 2023). "Peripheral IL-18 correlates with abnormal brain activity in patients with depression, suggesting that IL-18 is involved in the pathophysiological mechanism of depression." (PMID 37921965, 2023). "By analyzing 41 cytokines using the largest available GWAS datasets, we identified that a potential causal relationship between IL-18, IL-1β, and RANTES and depression." (PMID 37600668, 2023). "Increased levels of pro-inflammatory cytokines IL-6, IL-8, and IL-18 in nurses with moderately-severe depressive symptoms support a meta-analysis of inflammatory markers in depression studies that identify depression as a pro-inflammatory state." (PMID 37637801, 2023).
depression (continued). "It is suggested that exercise can inhibit proinflammatory factors TNF-α, IL-6, and IL-18 to improve depression." (PMID 37239191, 2023). "After controlling for all covariates, we found that the moderately severe depression group had increased IL-6 (p = 0.003), IL-8 (p = 0.001), and IL-18 (p = 0.023) levels but decreased IFN-γ (p = 0.003) levels." (PMID 37637801, 2023). "IL-18 serum levels have been found to be higher in major depressive disorder patients than in controls." (PMID 37921965, 2023). "Of note, IL-18 levels were also increased in mRNA-vaccinated patients that acquired myopericarditis and psychiatric disorders such as major depression and panic disorder." (PMID 37427401, 2023). "It has been suggested that pro-inflammatory cytokines (e.g., tumor necrosis factor, interleukin (IL)-1, IL-6, and IL-18) participate in the pathogenesis of RA and the development of depression in patients with RA." (PMID 36835939, 2023). "Serum or plasma levels of IL18 in patients with depression, AD, or mild cognitive impairment were found to be higher than in healthy individuals." (PMID 38139000, 2023). "COPD patients and depressive disorder patients present similar profiles of inflammatory biomarkers, such as IL-18, TGF-β, and RANTES, and interact with the inflammation, biomarker of the fibrinolytic system, uPAR." (PMID 37921965, 2023). "Previous studies have revealed that IL18 is closely related to several psychiatric disorders, including depressive disorders and schizophrenia." (PMID 38139000, 2023). "Patients with major depression exhibit significant inflammatory responses, including the increased expression of pro-inflammatory cytokines such as interleukin 6 (IL-6), interleukin 18 (IL-18) and tumor necrosis factor α (TNF-α)." (PMID 35334870, 2022). "The mice with knocked down NLRP1 inflammasome activity displayed diminished chronic stress-induced depressive-like demeanor, indicating that inflammasome-mediated IL-18-induced CNS inflammation can indeed lead to depression." (PMID 36614020, 2022). "Meanwhile, experiments have shown that the serum interleukin-18 (IL-18) is a potential marker for the development of depression." (PMID 36422003, 2022). "Pearson correlation analysis showed a positive correlation between IL-18 and age in patients with depression (r = 0.403, P = 0.018)." (PMID 35931995, 2022). "Interleukin-18 (IL18) is an inflammatory cytokine that is related to psychiatric disorders such as depression and cognitive impairment." (PMID 36151082, 2022). "The NLRP3 inflammasome pathway, a key target in depression, mediates the production of proinflammatory cytokines such as interleukin-1beta (IL-1beta) and interleukin-18 (IL-18)." (PMID 35237160, 2022). "IL-18 is a newly discovered proinflammatory cytokine, and higher circulating IL-18 has also been reported in patients with depression." (PMID 36422003, 2022). "This study suggests the involvement of IL-18 in the pathophysiological mechanism for depression and interference with brain activity." (PMID 35931995, 2022). "In the current study, we measured serum IL-18 levels and analyzed its relationship with depression-related brain region activity in patients and healthy controls." (PMID 35931995, 2022). "In patients with depression, DC of the left posterior cingulate gyrus was significantly and negatively correlated with serum IL-18 levels." (PMID 35931995, 2022). "This study found that the level of IL-18 in patients with depression was significantly higher than that in healthy controls." (PMID 35931995, 2022). "In Ps patients with comorbid depression, high serumconcentrations of IL-6 and IL-18, as well as IL-17A, were presumed to act as sharedinflammatory mechanisms." (PMID 34819201, 2021). "In our previous study, Il18−/− mice showed less motivation and had impaired learning and memory, which are clinically included in depression or dementia." (PMID 34708129, 2021).
depression (continued). "Clinical studies also show that pro-inflammatory cytokines, e.g. TNF-α, IL-1β, IL-6, CCL-2, and IL-18, increase in patients with depression or anxiety." (PMID 32010477, 2020). "Further analysis of this study population found that levels of pro-inflammatory cytokines, including IL-6 and IL-18, predicted subsequent depression in patients with ACS." (PMID 30890971, 2019). "Plasma IL-18 concentrations increase in people with major depressive disorder, followed by decreases in endogenous opioid levels in the left amygdala and right hypothalamus and increases in the right ventral tegmental area." (PMID 30832404, 2019). "Studies show that the NLRP3 inflammasome in blood cells of patients with MDD was activated, and the increased serum levels of IL-1β and IL-18 were positively correlated with Beck Depression Inventory (BDI) scores." (PMID 31814820, 2019). "Serum concentrations of IL-6, IL-18, 25-hydroxyvitamin D3, and cortisol in patients with psoriasis (n = 85) according to depression severity." (PMID 30092066, 2018). "IL-18 mRNA expression is elevated in subordinate rat models with depression with respect to dominant rats." (PMID 20113500, 2010). "Moreover, elevated IL-18 levels correlate with the severity of depression symptoms resulting from stress and with mechanisms responsible for the development of chronic pain." (PMID 40806635, 2025). "Elevated pro-inflammatory cytokines, such as IL-1β, IL-6, and IL-18, are frequently observed in patients with depression and may trigger neuroinflammatory processes along with peripheral inflammation." (PMID 40358153, 2025). "Moreover, a meta-analysis demonstrated elevated plasma levels of interleukin-3 (IL-3), interleukin-12 (IL-12), and interleukin-18 (IL-18) in patients with depression." (PMID 41226404, 2025). "The activation of NLRP3 and the release of IL-1β and IL-18 may be involved in the pathogenesis of depression through multiple mechanisms." (PMID 40497971, 2025). "Increased IL-18 level in the amygdala mediated depression-like behaviors in a mouse PSD model." (PMID 40529498, 2025). "IL-18 is another cytokine involved in the pathophysiology of depression." (PMID 40305200, 2025). "These analyses also show that a significant number of cytokines (including IL1α, IL1β, TNFα, IL2, IL12, IL18) and receptors (sIL-1RA, sIL-6R) are abnormally high in patients suffering from depression and that these disturbances are present in the acute and stability phases, in MDD and BD." (PMID 38499657, 2024). "Additionally, the inhibition of peripheral proinflammatory cytokines, including IL-18, and microglial inhibition via minocycline reduces depression-like behaviors." (PMID 38791125, 2024). "Therefore, the first purpose of this study was to clarify the difference in peripheral RvD1, NLPR3, IL-1β, Il-18, and IL-4 between the adolescent patients with depression and the healthy control group." (PMID 38627683, 2024). "Biological mechanisms could influence the relationship between MDD and IL-18 levels, with the timing and chronicity of the depression playing a critical role." (PMID 40226698, 2024). "Our previous studies have found that chronic unpredictable mild stress (CUMS) stimuli induced depression-like behaviors, increased levels of IL-1β and IL-18 and altered the microbiota, which suggested NLRP3 inflammasome might be activated." (PMID 37293210, 2023). "The polymorphic variants of IL6, IL18, and TNFA were associated with depression and SCZ." (PMID 37510364, 2023). "As a result of linear regression analysis conducted in the DeprVUR sample controlling for sex, ethnicity, and age, we observed significant effects of the PCLO rs2715157 A-allele (β = 0.67, p = 0.03) and the IL18 rs187238 C-allele (β = 0.73, p = 0.03) on BDI-measured depression." (PMID 37510260, 2023).